U3 (Small nucleolar RNA U3 )
Synonyms: LOC124905293
Gene: Small nucleolar RNA gene on chromosome X (69,692,956 to 69,693,155, forward strand). Ensembl gene ENSG00000212434.
Gene Ontology:
Biological process: RNA processing
Cellular component: nucleolus
Homologues: Orthologues: chimpanzee U3 (99% identical), macaque U3 (78% identical), rabbit U3 (50% identical), pig U3 (33% identical), rat LOC120098417 (30% identical). Paralogues in human: SNORD3E (81% identical), U3 (80% identical), SNORD3P1 (79% identical), U3 (78% identical), SNORD3G (77% identical), U3 (77% identical), U3 (76% identical), SNORD3D (75% identical), U3 (75% identical), U3 (74% identical), SNORD3H (74% identical), U3 (73% identical), and 13 more.